FAM90A10 (family with sequence similarity 90 member A10)
Synonyms: FAM90A10P
Tractability: No criterion of Open Targets' tractability assessment is met for any kind of drug.
Gene: Protein-coding gene on chromosome 8 (7,766,902 to 7,772,547, forward strand). Ensembl gene ENSG00000285950.
Subcellular location (Human Protein Atlas): Nucleoplasm; Nucleoli
Homologues: Orthologues: mouse Fam90a1b (28% identical), mouse Fam90a1a (27% identical), rat Fam90a1l1 (26% identical). Paralogues in human: FAM90A7 (98% identical), FAM90A16 (98% identical), FAM90A17 (98% identical), FAM90A18 (98% identical), FAM90A19 (98% identical), FAM90A8 (98% identical), FAM90A9 (98% identical), FAM90A13 (97% identical), FAM90A15 (97% identical), FAM90A23 (97% identical), FAM90A24 (97% identical), FAM90A14 (97% identical), and 9 more.